GPRC5A (G protein-coupled receptor class C group 5 member A)
Diseases named in the same sentence as GPRC5A in open-access papers (continued):
Sharing a sentence is not in itself a finding about the gene and the disease.
pancreatic cancer (continued). "To investigate whether GPRC5A promoted pancreatic cancer progression via the YAP1 pathway, we evaluated the relationship between GPRC5A and YAP1 in pancreatic cancer tissues and cells." (PMID 36735162, 2023). "Our experiments showed that GPRC5A could bidirectionally control the expression of YAP1 and its target genes at the transcriptional level in pancreatic cancer cells." (PMID 36735162, 2023). "Although two papers have explored GPRC5A function in pancreatic cancer, they did not provide evidence from in vivo experiments or show that blocking downstream molecules disrupted the effect of GPRC5A." (PMID 36735162, 2023). "It was noted that MYEOV could serve as a ceRNA by producing molecular sponging effects on hsa-miR-103a-3p and hsa-miR-107, thus affecting the role of GPRC5A, SERPINB5, EGFR, KRAS, EIF4G2, and PDCD4 on pancreatic cancer progression." (PMID 36358856, 2022). "In conclusion, our experimental data demonstrated that low miR-135b-5p level could affect GPRC5A by KLF4, thus hindering cell malignant phenotypes of pancreatic cancer, but the inhibitory effect could be reversed by overexpressing GPRC5A." (PMID 35027543, 2022). "Our further analyses of GPRC5A on MIA PaCa-2 cells' response to gemcitabine showed that knockdown of GPRC5A enhanced cell apoptosis without gemcitabine treatment; also, that administration of gemcitabine further enhanced pancreatic cancer cell apoptosis." (PMID 27415424, 2016). "However, the interaction between GPRC5A and YAP1 in pancreatic cancer is unclear." (PMID 36735162, 2023). "Interestingly, we downregulated YAP1 using siRNA with or without GPRC5A overexpression in pancreatic cancer cells." (PMID 36735162, 2023). "To investigate whether MYEOV acts as ceRNA to exert certain regulatory effects on genes such as GPRC5A, SERPINB5, KRAS, EGFR, EIF4G2, and PDCD4, we analyzed the differential expression of these genes in pancreatic cancer and normal pancreatic tissues by the GEPIA database." (PMID 36358856, 2022). "Our results suggest that MST1/2 and LATS1/2 protein did not change markedly based on modulation of GPRC5A expression, which indicated that the regulation of YAP1 by GPRC5A is independent of LATS1/2 kinase in pancreatic cancer cells." (PMID 36735162, 2023). "To further determine the role of YAP1 in GPRC5A-mediated function in pancreatic cancer, we upregulated YAP1 using YAP1 plasmid with or without downregulation of GPRC5A in pancreatic cancer cells." (PMID 36735162, 2023).
breast carcinoma (22 papers, 2009 to 2025). "As a member of the GPCR superfamily, abnormal expressions of GPRC5A are associated with tumorigenesis, while GPRC5A is also significantly expressed in breast cancer." (PMID 35255904, 2022). "GPRC5A disorders have been associated with a variety of cancers, including non-small-cell lung carcinoma, breast cancer, CRC, liver cancer, and gastric cancer." (PMID 33579281, 2021). "The present results suggested a protective role of GPRC5A in human breast cancer and investigated its underlying mechanism, facilitating the development of novel clinical treatments for patients with TNBC." (PMID 33680947, 2020). "Another recent study showed that the germline inactivating mutation c.183delG of GPRC5A is enriched in breast cancer patients carrying the 5382insC allele of BRCA1." (PMID 25621293, 2014). "GPRC5A is reported to play a tumor-suppressive role, and its down-regulation has been implicated in lung, pancreatic, colorectal, and breast cancer pathology, although its endogenous ligand remains unknown." (PMID 39083597, 2024). "A high prevalence of GPRC5A germline mutations have been identified in BRCA1-mutant breast cancer." (PMID 33680947, 2020). "In conclusion, the present study suggested that GPRC5A was downregulated in human breast cancer cell lines." (PMID 33680947, 2020). "The mRNA expression levels of GPRC5A were significantly lower in breast cancer cells compared with MCF10A control cells." (PMID 33680947, 2020). "Our data are in line with recent experiments in which knockdown of GPRC5A in MDA-MB-231 breast cancer cells promoted colony formation and proliferation." (PMID 32719397, 2020). "In summary, the present results suggested that GPRC5A promoted cell apoptosis by regulating the PI3K/Akt signaling pathway in breast cancer cells." (PMID 33680947, 2020). "Using an in silico assay, a previous study has suggested that GPRC5A is highly expressed in breast cancer, particularly in ER-positive breast cancer compared with the normal breast cancer cell line MCF-10A." (PMID 33680947, 2020). "The present data suggested that GPRC5A promoted cell apoptosis via the intrinsic apoptotic pathway in human breast cancer cells in vitro." (PMID 33680947, 2020). "In summary, the present study identified GPRC5A as a potential protective factor against breast cancer progression and provided novel insights on the mechanism of GPRC5A on TNBC cell apoptosis." (PMID 33680947, 2020). "And the results suggested that GPRC5A was downregulated in breast cancer cell lines compared to normal breast epithelial cell lines." (PMID 33680947, 2020). "The expression of GPRC5A in breast cancer cell lines was detected by real time PCR and western blot." (PMID 33680947, 2020). "In summary, the present data suggested that GPRC5A was downregulated in human breast cancer, especially in triple negative breast cancer." (PMID 33680947, 2020). "In breast cancer, the picture is diverse: According to the “bioportal” website, GPRC5A expression analysis revealed more breast tumor tissues with protein amplification than with deletions." (PMID 32719397, 2020). "Our previous researches implicate GPRC5A as a tumor suppressor in breast cancer cells, and GPRC5A exerts its tumor-suppressive function by inhibiting EGFR related cell proliferation." (PMID 33680947, 2020). "In breast cancer, GPRC5A has been reported to be downregulated and was identified to act as a tumor suppressor by RhoA/C and EGFR related signaling pathway." (PMID 33680947, 2020). "In sharp contrast, GPRC5A is highly expressed in breast cancer, colorectal and pancreatic carcinoma while its expression is low in the respective healthy tissues (for review see12)." (PMID 32719397, 2020).
breast carcinoma (continued). "GPRC5a is overexpressed in a variety of cancers, including colon cancer, breast cancer, and gastric cancer." (PMID 29949874, 2018). "Elevated GPRC5A mRNA expression has been observed in breast cancer cell lines and clinical tumor tissues (25 primary breast cancer tissues), and GPRC5A knockdown leads to inhibition of cell growth in cell lines MCF7 and T47D." (PMID 30417009, 2018). "GPRC5A and breast cancer: The evidence so far regarding GPRC5A's role in breast cancer has been conflicting." (PMID 25621293, 2014). "Another group found that in breast cancer, the expression of GPRC5A along with that of PYCARD and FXYD3 can serve as a good predictor of treatment outcome and enhances the predictive power of tumor size." (PMID 25621293, 2014). "In one breast cancer study it was shown that GPRC5A mRNA is up-regulated in 19 of 25 primary breast cancers and in 6 of 11 breast cancer cell lines examined, compared with normal mammary gland tissue." (PMID 25621293, 2014). "In addition, miR-497 targeted GPRC5A expression to curb chemotherapy resistance and metastasis of breast cancer cells." (PMID 35255904, 2022). "Therefore, the current study set out to explore how DNA methyltransferase 1 (DNMT1) affects breast cancer through mediating miR-497/GPRC5A axis." (PMID 35255904, 2022). "The obtained findings of our work revealed that DNMT1 may inhibit miR-497 expression and boost expression of GPRC5A through DNA methylation, thus augmenting chemotherapy resistance and metastasis in breast cancer." (PMID 35255904, 2022). "Cultured breast cancer cells were used in the present study to detect the expression of GPRC5A." (PMID 33680947, 2020). "First, the expression of GPRC5A in breast cancer cells was examined." (PMID 33680947, 2020). "However, the present results suggested that the expression of GPRC5A was decreased in cultured breast cancer cells, in line with a previous study." (PMID 33680947, 2020). "Thus, the role and mechanism of GPRC5A in breast cancer, especially in different breast cancer subtypes, still need elucidated for further application of GPRC5A as a prospective clinical target." (PMID 33680947, 2020). "The detailed role of GPRC5A in human breast cancer was then investigated." (PMID 33680947, 2020). "In the present study, GPRC5A was identified to be downregulated in breast cancer cells." (PMID 33680947, 2020). "However, the diverse role of GPRC5A in tumor formation is reflected by recent studies with breast cancer cell lines." (PMID 32719397, 2020). "Similarly, the protein expression levels of GPRC5A were significantly lower in breast cancer cells compared with the MCF10A." (PMID 33680947, 2020). "Meanwhile, we found GPRC5A as a tumor suppressor has effect on breast cancer cell apoptosis." (PMID 33680947, 2020). "Additionally, GPRC5A is significantly downregulated in TNBC breast cancer compared to ER+ and HER2+ breast cancer from TCGA database." (PMID 33680947, 2020). "A tumor-suppressive effect of GPRC5A has been shown in MDA-MB-231 breast cancer cells." (PMID 32719397, 2020). "Here, we analyzed the function of GPRC5A in breast epithelial and breast cancer cells." (PMID 32719397, 2020). "However, there are many papers that have reported that the higher expression of GPRC5a correlated with a worse survival rate in colon cancer, breast cancer, and gastric cancer." (PMID 29949874, 2018). "All these results reveal a tumor-promoting role of GPRC5A in breast cancer." (PMID 30417009, 2018). "Moreover, knockdown of GPRC5A by small interfering RNA (siRNA) in breast cancer cell lines MCF7 and T47D suppressed cancer cells' growth." (PMID 25621293, 2014). "Moreover, a prior study documented notably increased expressions of GPRC5A in breast cancer." (PMID 35255904, 2022). "Furthermore, we conducted CCK-8, flow cytometry, Transwell and scratch assays in MCF-7/ADR cells to validate whether miR-497 affected breast cancer progression by regulating the GPRC5A expression." (PMID 35255904, 2022).
breast carcinoma (continued). "Collectively, our findings indicated that DNMT1 may inhibit miR-497 and boost the expression of GPRC5A through methylation, thus augmenting breast cancer chemotherapy resistance and metastasis, which provides novel mechanistic insight into the unrecognized roles of DNMT1 in breast cancer." (PMID 35255904, 2022). "GPRC5A could be a malignant biomarker in breast cancer progression." (PMID 33680947, 2020). "Chromosome 13 open reading frame 42 (C13orf42), lactalbumin alpha (LALBA), G protein-coupled receptor class C group 5 member A (GPRC5A), and GC vitamin D binding protein (GC) have been identified as the most highly expressed genes in breast cancer." (PMID 40608007, 2025). "This is consistent with the results of previous published experiments with the breast cancer cell lines T47D and MCF7, which showed a growth-inhibiting effect of GPRC5A-siRNA." (PMID 28114355, 2017). "Altogether, DNMT1 inhibits miR-497 and elevates GPRC5A expression through methylation to promote chemotherapy resistance and metastasis in breast cancer, which sheds a new light on the anti-tumor significance of DNMT1 in regard to breast cancer." (PMID 35255904, 2022). "GPRC5A exhibited the lowest expression levels in TNBC compared to ER+ and HER2+ breast cancer." (PMID 33680947, 2020). "Notably, MDA-MB-231 and MDA-MB-468 cells exhibited the lowest expression levels of GPRC5A, while T47D and MCF7 cells exhibited the highest mRNA expression levels of GPRC5A among the breast cancer cell lines investigated." (PMID 33680947, 2020). "Furthermore, GPRC5A together with FXYD domain-containing ion transport regulator 3 (FXYD3) and PYCARD have been reported as potential predictors of pathological grading of breast cancer and might benefit the management of clinical treatments." (PMID 30417009, 2018).
gastric cancer (17 papers, 2014 to 2025). A primary or metastatic malignant neoplasm involving the stomach. "This raises the possibility that GPRC5A can be used as a potential biomarker and a treatment target for gastric cancer based on its membrane localization and its association with cancer cell proliferation." (PMID 25621293, 2014). "Abnormal expression of GPRC5A has been unraveled in various types of tumors, such as prostate cancer, gastric cancer and colorectal cancer." (PMID 33543830, 2021). "Hsa_circ_006100 functions as an oncogene in gastric cancer and exerts its effects via miR‐195/GPRC5A signalling." (PMID 31318114, 2019). "GPRC5A and gastric cancer: In normal small intestine, GPRC5A is expressed at very low levels whereas in gastric cancer tissues GPRC5A is elevated significantly." (PMID 25621293, 2014). "The pattern of GPRC5A expression in gastric cancer tissues is quite different from that of normal mucosa and of adjacent noncancerous lesion samples." (PMID 25621293, 2014). "MiR-195 is under-expressed in GC, which is associated with high TNM stage, poor cell differentiation, and lymph node metastasis, and miR-195 plays a tumor suppressive role in gastric cancer by regulating G protein-coupled receptor, family C, group 5, member A (GPRC5A)." (PMID 40296904, 2025). "Mechanistically, GPRC5A was predicted as a target of miR‐195 and was upregulated in gastric cancer." (PMID 31318114, 2019). "Global gene expression profiling revealed that GPRC5A was significantly elevated in gastric cancer and may act as a potential biomarker." (PMID 29283424, 2017). "For the first time, we identified that CKS1B, CXCL1, and GPRC5A are putative targets of miR-204 and elucidated that miR-204 acted as potential tumor suppressor and, therefore, are useful as a promising therapeutic target for gastric cancer." (PMID 29283424, 2017). "In gastric cancer, GPRC5A expression levels are elevated in GC tissues compared with normal tissues and high expression of GPRC5A is significantly related to aggressive clinicopathological parameters and poor OS." (PMID 33788883, 2021). "In gastric cancer, ENO1 promotes tumor growth 45 by stabilizing the expression of genes such as SOX9, VEGF-α, GPRC5A, and MCL-1." (PMID 40303285, 2025). "For example, expression of CDKN1C, RASSF7, GPRC5A, and MPZL2 were all significantly related to KLF5 in gastric cancer tissue." (PMID 33923166, 2021). "In addition, miR-204 has also been found to inhibit the proliferation of gastric cancer cells by targeting CKS1B, CXCL1, and GPRC5a." (PMID 34950208, 2021). "Besides, miR-204 can inhibit GPRC5A expression via binding to its 3' UTR in gastric cancer (GC)." (PMID 30417009, 2018).
lung adenocarcinoma (14 papers, 2010 to 2024). A carcinoma that arises from the lung and is characterized by the presence of malignant glandular epithelial cells. "Therefore, the study of Gprc5a-deficient mice may help to unveil the cells of origin in lung adenocarcinomas." (PMID 32157214, 2020). "Further analysis of The Cancer Genome Atlas (TCGA) database showed that the mRNA level of TNF-α, a key cytokine responsible for NF-κB activation, was inversely correlated with GPRC5A expression in lung adenocarcinoma (LUAD)." (PMID 36413416, 2023). "We used Gprc5a-knockout (KO) mice, the first animal model of spontaneous lung adenocarcinoma established by the deletion of a single lung tumor suppressor gene." (PMID 32157214, 2020). "G-protein-coupled receptor family C group 5 member A (Gprc5a) knockout (KO) mice are the first animal model that develops spontaneous lung adenocarcinoma through the deletion of a single lung tumor suppressor gene." (PMID 32157214, 2020). "The results showed that, GPRC5A expression (black bar) was high in lung tissues, but significantly reduced in human lung adenocarcinoma (LUAD) and lung squamous cell carcinoma (LUSC) although its expression in other type of tumors (red) was upregulated." (PMID 32060421, 2020). "Gprc5a-knockout (ko) mice developed spontaneous lung adenocarcinoma, indicating that Gprc5a is a lung tumor suppressor gene." (PMID 32060421, 2020). "In conclusion, we have found that treatment of Gprc5a-knockout mice with the tobacco-specific carcinogen NNK increased the rate of lung adenocarcinoma development compared to the spontaneous rate in control mice." (PMID 20686609, 2010). "Immunohistochemical analysis demonstrated the up-regulation of the protein levels of Mcm2, Fen1, Ube2C and cyclin D1 in lung adenocarcinoma tissue of NNK-exposed Gprc5a-knockout mice compared to the levels in normal lung tissue obtained from the same mice." (PMID 20686609, 2010). "Although we had been able to isolate only a single pair of Gprc5a−/− normal lung epithelial cells and lung adenocarcinoma cells from an NNK-exposed mouse, we were successful in deriving an NNK-ADC expression signature." (PMID 20686609, 2010). "Previous studies have reported decreased expression of GPRC5A in the bronchial epithelium of patients with COPD, and mice lacking GPRC5A were more susceptible to inflammation and lung adenocarcinoma." (PMID 38448858, 2024). "We performed 16S rRNA-Seq of fecal and lung samples collected prior to and at several timepoints following (nicotine-specific nitrosamine ketone/NNK) exposure in Gprc5a−/− mice that were previously shown to exhibit accelerated lung adenocarcinoma (LUAD) development following NNK exposure." (PMID 36142843, 2022). "GPRC5A is mainly expressed in end bronchiolar epithelium, and Gprc5a −/− mice are sensitive to silica-induced tumorigenesis and is downregulated in lung adenocarcinomas." (PMID 32778128, 2020). "Gprc5a-KO mice could spontaneously develop lung adenocarcinoma, indicating the cancerous cells can be generated when GPRC5A is deficient." (PMID 32157214, 2020). "We recognize that using an expression signature signifying lung adenocarcinoma development in the NNK-exposed Gprc5a knockout mouse model based on a single pair or normal and tumor cells and without a complimentary set of data from another pair of samples represents a potential limitation." (PMID 20686609, 2010). "Recently, it was reported that Gprc5a-/- mice spontaneously developed lung adenocarcinomas with or without chronically nicotine-specific carcinogen exposure." (PMID 33753999, 2021). "Gprc5a knockout mice do not show developmental abnormalities or phenotypic changes in the lung, but develop spontaneous lung adenocarcinomas." (PMID 33187367, 2020).